Y_RNA (Y RNA )
Gene: Miscellaneous RNA gene on chromosome 17 (32,830,219 to 32,830,329, reverse strand). Ensembl gene ENSG00000201178.
Homologues: Orthologues: chimpanzee Y_RNA (99% identical), macaque Y_RNA (95% identical). Paralogues in human: Y_RNA (91% identical), RNY1 (89% identical), Y_RNA (89% identical), Y_RNA (88% identical), RNY1P11 (87% identical), Y_RNA (87% identical), Y_RNA (86% identical), Y_RNA (85% identical), RNY1P10 (84% identical), RNY1P7 (84% identical), Y_RNA (84% identical), RNY1P8 (83% identical), and 100 more.